INS (insulin)
Diseases named in the same sentence as INS in open-access papers (continued):
Sharing a sentence is not in itself a finding about the gene and the disease.
Hypoglycemia (continued). "However, the ITT did show that fenofibrate-treated mice had an earlier return to normal glucose levels from insulin-induced hypoglycaemia (p = 0.016)." (PMID 31410530, 2019). "The odds of hypoglycemia associated with SBB vs. carvedilol was not significantly different in basal insulin non-users (OR 1.90, 95% CI 0.90–4.02, p = 0.09) or users (OR 0.50, 95% CI 0.22–1.14, p = 0.10)." (PMID 31775749, 2019). "Therefore, to better understand the effects of the glucogenic treatments on hypoglycemia and hyperketonemia, we determined simultaneous effects on circulating concentrations of insulin." (PMID 31561613, 2019). "GLP-1 controls glucose homeostasis by accelerating insulin secretion in a glucose-dependent manner, but it is not prone to a hypoglycemia risk compared with traditional hypoglycemic drugs because of its modulation of glucose-dependent insulin secretion." (PMID 31772770, 2019). "In critically ill patients there is a risk of hypoglycaemia-related morbidity associated with intensive glucose control with intravenous insulin, although we did not have data on acute glucose control in our study." (PMID 31815634, 2019). "The lower frequency of nocturnal hypoglycemic episodes observed with short-acting insulin analogues may contribute to the lower frequency of severe hypoglycemia." (PMID 30622653, 2019). "For other medications with a risk of hypoglycemia (sulfonylureas, glinides), a modification of the dosage is not recommended, but similar to insulin therapy, a particular attention after the test is necessary." (PMID 31611821, 2019). "Although it has been suggested that this afferent nerve signalling may be part of a metabolic reflex to hypoglycemia, until now, no studies have examined neural responses in the vagus nerve to insulin-triggered hypoglycemia." (PMID 32232099, 2019). "Importantly, the insulin-mediated hypoglycemia occurred in both WT and KO mice (WT n = 8; KO n = 5), suggesting that both genotypes were sensitive to CL’s effect." (PMID 30804793, 2019). "Peripheral insulin use may result in deleterious effects to the brain, due to its tendency to induce hypoglycemia." (PMID 30768625, 2019). "Furthermore, Sub mice showed a marked hypoglycemia, reduction of insulin levels, increase in GSK3 activity and elevation of IGF-1 serum levels, as well as low skin surface temperature and body weight." (PMID 31707362, 2019). "The hypoglycemia group included not only insulin users but also users of DPP-4 inhibitor." (PMID 30815039, 2019). "Diagnosis is established with a 72-hour fast through documentation of hypoglycemia with characteristic symptoms that are rapidly reversed by glucose administration and with demonstration of inappropriately increased plasma insulin, c-peptide, and/or proinsulin, in the setting of hypoglycemia." (PMID 31263451, 2019). "However, it is noted that more patients experienced hypoglycaemia and uncorrected hypoglycaemia in this cohort suggesting worse outcomes when the nuclear medicine specialist modifies the recommended insulin dose." (PMID 30737563, 2019). "Furthermore, we considered that the low hypoglycemia frequency found in group G is related to the effect of the small sample size or differences in background, such as insulin secretion and complications." (PMID 31486247, 2019). "The global Hypoglycemia Assessment Tool (HAT) study, which was designed to determine the incidence of hypoglycemia in a global insulin-treated patient population, demonstrated that the real-world incidence of hypoglycemia is high compared with rates reported from randomized clinical trials." (PMID 31584770, 2019). "As such, LCDs may enable more accurate estimates of carbohydrate content at mealtime, and as such exogenous insulin needs, to subsequently reduce glucose variability and incidence of hypoglycaemia." (PMID 31067747, 2019).
Hypoglycemia (continued). "Stimulation of insulin production through activation of beta-2 adrenoceptors may also impact glucagon secretion and contribute to reactive hypoglycemia." (PMID 31275775, 2019). "In addition, hypoglycemia occurs in approximately 70% of women who use insulin some time during their pregnancy." (PMID 31781670, 2019). "It remains unclear whether short-acting insulin analogues are indeed superior to regular human insulin in reducing hypoglycemia and lowering postprandial glycemia." (PMID 30622653, 2019). "This improved performance is achieved with higher insulin rates and higher carbohydrate intake, but no loss in safety from hypoglycaemia." (PMID 31640720, 2019). "Compared with insulin, glyburide had a higher increase of neonatal hypoglycemia." (PMID 31781670, 2019). "Exercise-induced hypoglycemia may be a result of blunted glucagon response, reduced adrenomedullary response, and diminished clearance of injected insulin." (PMID 30781593, 2019). "Furthermore, insulin users who developed hypoglycemia were often using an insulin mixture, and one of these patients developed severe hypoglycemia." (PMID 30815039, 2019). "Hypoglycemia related ADRs were ‘hyper-insulinemic hypoglycemia’ and ‘increased blood insulin’." (PMID 31462666, 2019). "Furthermore, in the low HbA1c groups, insulin secretion was lower and the incidence of hypoglycemia were high among insulin users, suggesting that strict blood glucose control can induce hypoglycemia." (PMID 30815039, 2019). "Several clinical trials also showed a consistent reduction in HbA1c when DPP-4 inhibitors were added to basal insulin therapy, with no increased risk of hypoglycemia." (PMID 31366085, 2019). "Based on morphological measures, minocycline administration attenuated insulin-induced microglia activation in the arcuate nucleus, which was accompanied with improved glycemic control, elevated plasma catecholamine levels and less severe hypoglycemia." (PMID 30996341, 2019). "However, there is no consensus approach and complications of previously proposed insulin guidelines included significant hypoglycaemia, inconvenience and skeletal muscle uptake." (PMID 30737563, 2019). "In randomized clinical trials in which basal insulin dose was titrated seeking a predefined self-monitored plasma glucose target, this translated into less hypoglycemia and apparently lower glycemic fluctuation with the same efficacy in terms of HbA1c reduction." (PMID 30369394, 2019). "Patients with hypoglycemia of Groups 1 were high among insulin users (5.1%, p = 0.015)." (PMID 30815039, 2019). "With each pre-exercise announcement strategy, the algorithm was able to attenuate insulin delivery to reduce the risk of immediate and delayed exercise-related hypoglycemia, with no instances of overnight hypoglycemia." (PMID 30925077, 2019). "The primary outcome was the incidence of hypoglycemia within 12 hours of insulin administration." (PMID 30890150, 2019). "Moreover, CGM is found to be inaccurate during hypoglycemia episodes, that is, insulin-induced hypoglycemia versus spontaneous hypoglycemia." (PMID 31042157, 2019). "Indeed, in addition to the side effects of treatment (hypoglycemia, malaise, etc.), the use of insulin therapy is very controversial." (PMID 31227028, 2019). "In Group 1, the percentage of insulin users was high among the hypoglycemia cases." (PMID 30815039, 2019). "However, an insulin infusion protocol must meet both safety and efficiency requirements, and the main rules for hypoglycaemia management should be clearly defined." (PMID 30689675, 2019). "Insulin pumps enable greater flexibility in insulin adjustment as basal rates can be reduced or stopped before during or after exercise to prevent exercise mediated hypoglycemia." (PMID 31258513, 2019).
Hypoglycemia (continued). "The major effects of ghrelin are linked to mechanisms involved in avoiding starvation and promoting food intake and include stimulation of GH secretion to restrict peripheral glucose uptake, promote lipolysis, and suppress insulin secretion to prevent hypoglycemia." (PMID 31692759, 2019). "In addition to minimising the risk of unrecognised hypoglycaemia, regular 15-minutely BGL monitoring after insulin administration until it reaches a nadir enables identification of the resolution of physiologic insulin effect." (PMID 30737563, 2019). "All other antidiabetic medications when used either as monotherapy or in combination therapy without insulin or sulfonylureas are rarely, though not never, associated with hypoglycemia, and the risk is therefore considerably less though still a consideration." (PMID 31003482, 2019). "Iatrogenic hypoglycemia remains a major barrier to effective treatment of insulin-treated diabetes." (PMID 30252067, 2019). "The main benefit was less incidence of hypoglycemia in the reduced insulin treatment group." (PMID 31828166, 2019). "The insulin and C-peptide levels were found to be markedly elevated during the hypoglycemia." (PMID 31426870, 2019). "Mimicking the effects of bariatric surgery in obese and/or diabetic patients and reducing enteroendocrine activity in insulin-sensitive patients experiencing post-surgical hypoglycemia are both promising areas for developing new and effective treatments in the metabolic field." (PMID 30726726, 2019). "The aim of the present systematic review and meta-analysis was to evaluate the outcomes (all hypoglycemic episodes, nocturnal and severe hypoglycemia, and postprandial glycemia) associated with the use of short-acting insulin analogues in T1DM as compared to regular human insulin." (PMID 30622653, 2019). "Moreover, by using a sham-saline group, we specifically controlled for the immunological effects of insulin, thereby robustly investigating proinflammatory changes in response to hypoglycemia." (PMID 30252067, 2019). "We also injected naloxone 2 h after insulin-induced hypoglycemia to determine whether a more physiologically relevant time frame of administration would recover the epinephrine response." (PMID 31013147, 2019). "Hypoglycemia is even more common among insulin-treated hospitalized patients." (PMID 31775749, 2019). "Children and adolescents with Type 1 DM may develop hypoglycemia because of increased glucose utilization that results from excessive insulin dosing, skipping meals or reduced insulin requirements during exercise." (PMID 31651281, 2019). "Hypoglycemia is a common complication of insulin treatment in patients with DM." (PMID 29721018, 2018). "This study showed that erroneous estimation of meal insulin boluses did not increase the risk of hypoglycemia assessed by time <4.0 mmol/L with a simplified meal bolus strategy and dual-hormone closed-loop delivery." (PMID 29422651, 2018). "Initiate insulin as per the clinical situation, but keep a close watch for hypoglycemia." (PMID 29508275, 2018). "A recent consensus published in JAPI 2017 recommends that premix insulin analogues may be preferred over human premix insulins due to the lower incidence of major and nocturnal hypoglycemia and flexibility of administration." (PMID 29527102, 2018). "The episodes of hyperinsulinism with secondary hypoglycemia reported here might result from a reduced hepatic degradation of insulin due to the high blood volume bypassing the liver." (PMID 30415638, 2018). "Nocturnal hypoglycemia was reduced in insulin analogues in 35% (OR 0.65; 95% CI 0.55;0.77)." (PMID 29649221, 2018). "Introducing basal insulin analogues in persons with T2DM previously inadequately controlled on other insulin types can significantly improve glycemic control and reduce the risk of hypoglycemia, without adversely affecting body weight." (PMID 29460260, 2018).
Hypoglycemia (continued). "It is possible that the increased glucose levels at the later time points with botanical supplementation in the insulin tolerance test is due to counterregulatory mechanisms against hypoglycemia since these mechanisms occur in male mice at 80 mg/dl glucose, a level observed in the female mice." (PMID 30208938, 2018). "Simply turning off insulin delivery upon sensing the start of activity, however, may be insufficient to completely prevent declines in blood glucose, and subsequently hypoglycemia, unless exercise is performed shortly after a meal." (PMID 30524371, 2018). "The hypoglycemia and low TG might be attributed to the markedly elevated blood insulin level; and the total cholesterol (TCh) and low-density lipoproteins-cholesterol (LDL-c) also showed a decreasing trend." (PMID 29789568, 2018). "Similarly, in ITT, after four weeks of fructose intake, the hypoglycemia nadir in 4FDR was at the same time point as 4NDR, albeit significantly steeper, indicating towards the onset of impairment of insulin signaling cascade." (PMID 30374065, 2018). "This may reflect a causal association (those with low C-peptide and high glucose variability are likely to need prandial insulin for glycaemic control), although insulin regimen may directly influence hypoglycaemia." (PMID 28983693, 2018). "Postprandial reactive hypoglycaemia appears within a few hours after high-GI meal consumption, when blood glucose concentrations begin to decline rapidly, primarily due to an exaggerated increase in insulin secretion, thereby resulting in hunger." (PMID 30044398, 2018). "The differential diagnosis of hypoglycemia can be categorized into exogenous drugs, increased glucose utilization, decreased glucose delivery, decreased glucose production, increased insulin production, and decreased insulin clearance." (PMID 29849273, 2018). "In contrast to the benefits, there is a concern that bolus insulin administration may result in hypoglycemia and hypokalemia." (PMID 30544554, 2018). "Similarly, the incidence of serious hypoglycemic episodes and nocturnal hypoglycemia was lower during the 6-month study period than over the same time period preceding basal insulin analogue treatment (p < 0.001 vs. 6 months before insulin analogue treatment)." (PMID 29460260, 2018). "Outcomes of interest included blood glucose, frequency of hypoglycaemia and insulin administration." (PMID 30428906, 2018). "The injection of insulin into a site of lipodystrophy may lead to erratic absorption of the insulin, with the potential for poor glycemic control and unpredictable hypoglycemia." (PMID 30116742, 2018). "The superiority of SGLT2 inhibitors shows in reducing the glucose level independent of insulin secretion, lowering the risk of hypoglycemia, and improving cardiovascular outcomes." (PMID 30670968, 2018). "While insulin treatment can effectively reduce HbA1c levels in patients, the pharmacokinetic characteristics of human insulin mean that it is sometimes difficult to avoid glycemic fluctuations and even hypoglycemia." (PMID 29520742, 2018). "However, one case report of two episodes of hypoglycemia secondary to metformin toxicity was a previously healthy patient, who had normal nutritional status, and co-ingestion of sulfonylurea and insulin use was excluded by extensive laboratory tests." (PMID 30119705, 2018). "Hypoglycaemia was identified by HCPs as having an effect on insulin adherence." (PMID 29788908, 2018). "Sensor-augmented pumps (SAPs) can suspend insulin delivery for actual or predicted hypoglycaemia." (PMID 29423581, 2018). "Multiple studies suggest that the effects of insulin-induced hypoglycemia on serum potassium may be the main mechanisms of direct or indirect activation of membrane-bound Na+/K+ ATPase." (PMID 30105256, 2018). "However, most patients and physicians are reluctant to initiate insulin early due to fear of injection, hypoglycemia, weight gain, and other complications." (PMID 29527102, 2018).
Hypoglycemia (continued). "The correct dose of insulin is the one which achieves the best attainable glycemic control for an individual child or adolescent without causing obvious hypoglycemia problems." (PMID 30190702, 2018). "However, long-term follow-up of a larger number of patients in this center showed that only 28% remained insulin-independent, although persistent graft function still protected against hypoglycemia and improved glycemic control [41••]." (PMID 30250968, 2018). "In conclusion, hybrid closed‐loop intervention reduces the risk of hypoglycaemia, particularly during the night, with a swift recovery from hypoglycaemia during the day, and leads to slightly elevated 2‐hour post‐hypoglycaemia glucose levels compared to those with insulin pump therapy." (PMID 29577536, 2018). "Human intermediate basal insulin (Neutral Protamine Hagedorn, NPH) is often the initial choice, but, with its duration of action of 12–18 h, it is associated with a risk of hypoglycemia and may require multiple injections during the day." (PMID 29460260, 2018). "Since the administered glucose was rapidly cleared from the circulation and insulin levels were not decreased in the hypoglycemic infected Adx mice, we tested whether suppression of insulin release could alleviate the hypoglycemia." (PMID 30375380, 2018). "Hence, an insulin source that regulates glucose levels on a minute-by-minute basis to prevent hypoglycaemia and diabetic complications and to improve quality of life and life expectancy is required." (PMID 29306997, 2018). "TCPTP-deficiency in POMC-TC mice increased c-Fos staining (a surrogate marker of neuronal activation) in the PVH of fasted mice and this was exacerbated by insulin; although systemic insulin administration resulted in hypoglycemia, this was similar in Ptpn2fl/fl and POMC-TC mice." (PMID 30230471, 2018). "As fear of nocturnal hypoglycemia is also thought to be one of the major factors reducing adherence to treatment, those receiving basal insulin analogues may be more likely to adjust their insulin doses to achieve treatment goals." (PMID 29460260, 2018). "Meta-analysis of 15 studies demonstrated that the combination of GLP-1 RA and basal insulin, in comparison with other anti-diabetic treatments, can enable achievement of robust glycemic control, without increased risk of hypoglycemia and weight gain." (PMID 29563974, 2018). "Our study included the subjects with hypopituitarism who had inadequate counterregulatory hormonal responses and thus might result in more profound systemic changes in insulin-induced hypoglycemia." (PMID 30105256, 2018). "Given high levels of anti-insulin antibodies, hyperinsulinemia, late postprandial hypoglycemia, and clinical presentation coinciding with starting captopril use, the diagnostic hypothesis of IAS was proposed and captopril was discontinued." (PMID 30462811, 2018). "Participants on sulfonylureas and/or insulin had higher rate of hypoglycaemia." (PMID 29884151, 2018). "Evidence suggests that basal insulin analogues like glargine and detemir were effective and safe without any risk of hypoglycemia and weight gain." (PMID 29527102, 2018). "This is in marked contrast with observational studies that show that severe hypoglycaemia rates remain comparable with those reported over 20 years ago, despite the introduction of insulin analogues, continuous subcutaneous insulin infusion (CSII) and continuous glucose monitoring (CGM)." (PMID 28660491, 2018). "However, clonidine treatment did not significantly improve the survival of the mice and was, despite dramatically decreased insulin levels, unable to restore or increase glycemia in most of the mice that developed hypoglycemia." (PMID 30375380, 2018). "Hypoglycaemia was identified in survey participants as a key barrier and concern for patients with impact on their emotional state, daily functioning and engagement with their insulin." (PMID 29788908, 2018).